TNF (tumor necrosis factor)
Diseases named in the same sentence as TNF in open-access papers (continued):
Sharing a sentence is not in itself a finding about the gene and the disease.
tumor (continued). "Mature DCs can first secret IL-1β, IL-2, IL-6, TNF-α, and IFN-γ to promote the differentiation of T cells into CD8+ subset and then activate those CD8+ T cells to CTLs through the cross-presentation of tumor antigen peptides with major histocompatibility complex class I (MHC I)." (PMID 35836249, 2022). "Moreover, the tumor-bearing KO mice had decreased frequencies of tumor-infiltrating IFN-γ–producing, TNF-α–producing, and granzyme B–producing CD8+ T cells." (PMID 35143421, 2022). "Therefore, the authors determined the content of CASP3, TNFα, and IL6 inflammatory factors in the serum of the xenograft tumor model." (PMID 35815259, 2022). "TNF-α alone had no noticeable effect on tumor growth (i.e., the normalized tumor size increase = 35.6, p = 0.6905)." (PMID 36678748, 2022). "This ICD induction increases the serum levels of proinflammatory cytokines, such as TNF-α, IL-6, and IFN-γ, while also improving the tumor infiltration of CD4+ and CD8+ cells, eradicating the primary tumor, and preventing lung metastasis through an abscopal effect." (PMID 35214129, 2022). "Murine tumour models also demonstrated that endothelial cells exposed to bFGF and long-term VEGF display reduced ICAM-1 and VCAM-1 expression as well as decreased expression of TNF-α induced CXCL10 and CXCL11 T-cell chemoattractants." (PMID 36045675, 2022). "For example, GNPs have been efficiently used to deliver tumor necrosis factor-alpha (TNF-α) to tumor sites and its nontoxicity has been validated in a phase I clinical trial." (PMID 35213967, 2022). "Tc cells secrete pro-inflammatory cytokines TNF and IFN-γ that have cytotoxic effects on tumor cells, further, Tc cells can directly kill cells through secretion of perforin and granzyme B that generate pores in the plasma membrane and activate cellular caspases, respectively." (PMID 36072595, 2022). "In this tumor context, the activation of the immune system will lead to the secretion of anti-cancer cytokines, such as Interferon-gamma (INF-γ), TNF-α, and IL-6, and cell phagocytosis to eliminate the tumor, thus becoming a tool for the development of new treatments in cancer therapy." (PMID 36011024, 2022). "In our cell experiments, TNF-α and IL-6 were highly expressed in PRAD cell lines and positively regulated by ARRB2, suggesting that ARRB2 could affect PRAD tumor progression by regulating the expression of IFs." (PMID 36284990, 2022). "Infliximab and adalimumab, two immune checkpoint inhibitors that could blockade TNF, TNFRSF1A, and TNFRSF1B, were also included in the network, further highlighting the potential utilities in tumor immunotherapy of TNBC." (PMID 36291687, 2022). "The negative correlation between TNF-α expression and immune checkpoint blockade response suggests the role of B cells in tumour growth via inflammatory cytokines production." (PMID 35334544, 2022). "Consequently, the secretion of cytokines, such as TNF-α and IFN-γ, was elevated, and antitumor immunity was activated, resulting in effective tumor growth inhibition." (PMID 36145656, 2022). "Moreover, outside of the tumor, splenic CD8 T cells from lean and obese mice secreted similar levels of IFN-γ, TNF, and GzmB and expressed similar levels of CD69, CD44, CD36, Eomes, and T-bet." (PMID 35103755, 2022). "At the 70% ERα+/ERα−ratio, MDA-MB-231Trans−ER and MDA-MB-231WT cell models showed the strongest cell invasion and migration in vitro as well as the highest M2 macrophage polarization and VEGR, TNF-α, BRCA1, and HER2 expression levels in the tumor microenvironment." (PMID 36118080, 2022). "Tumor cell recognition by CD4+ T cells is also fundamental to tumor cell elimination by direct release of the proinflammatory cytokines interferon (IFN)-γ and tumor necrosis factor (TNF)-α, and by modulating the activity of other immune cells including CD8+ CAR T cells." (PMID 36591284, 2022).
tumor (continued). "By using cell counts, we found that IL-9 did not influence the tumor cell count, while IFN-ɣ and TNF-alpha decreased the overall tumor cell count." (PMID 35514957, 2022). "Follow-up studies have found that endogenous TNF-α derived from tumor cells and macrophages at the tumor site does not have antitumor activity but rather promotes tumor growth and metastasis." (PMID 35965509, 2022). "It was shown that TNF-α and IFN-γ secretion is defective in PKC-θ−/− mice, and this can contribute to defective recruitment of effector cells to the site of tumor development." (PMID 35258455, 2022). "Monocytes and macrophages are the major sources of numerous cytokines, including tumor necrosis factor alpha (TNF), interleukins, colony-stimulating factors, chemokines and cytotoxic mediators, which appear to play an important role in the regulation of tumor growth." (PMID 35778697, 2022). "For tumor cells, STAT3 decreases the production of immuno-stimulatory cytokines such as interferon-γ (IFN-γ) and tumor necrosis factor-α (TNF-α), along with elevated expression of immuno-exhausting cytokines (IL-6, IL-10, transforming growth factor-β [TGF-β], and VEGF)." (PMID 36080223, 2022). "Since MAP4K4 also belongs to the Ste20 family and is activated by TNFα to participate in the JNK signaling pathway, we hypothesized that MAP4K4 may act upstream of MLK3 to promote tumor development." (PMID 36292671, 2022). "TAMs induce EMT in tumor cells by secreting a host of cytokines and growth factors, such as transforming growth factor-beta (TGF-β), tumor necrosis factor-α (TNF-α), interleukin-6 (IL-6), and interleukin-8 (IL-8), thereby promoting tumor invasion and metastasis." (PMID 35965509, 2022). "For instance, tumor-derived VEGF-A, TGF-β, and TNF-α may induce S100A8 expression in macrophages and endothelial cells, or monocyte/macrophage-derived factors may stimulate its expression in cancer cells." (PMID 35954190, 2022). "Besides, activated CD8+ T cells secrete multiple cytokines such as INF-γ, TNF-α and TNF-β to regulate and improve overall anti-tumor response, including innate and specific immune systems." (PMID 35864520, 2022). "As observed in preclinical studies, the lower anti-tumor activity of high-dose NGR-hTNF (45 μg/m2) seemed to be related to the induction of soluble TNF-receptors shedding in the circulation, i.e., the release of TNF inhibitors." (PMID 35890309, 2022). "The absence of CXCR3 seems not to interfere with the ex vivo-specific lysis against tumor cells (OT-I CD8 T cells/OVA-expressing tumor cells) nor with the IFNγ, TNFα or Granzyme B expression." (PMID 36429101, 2022). "The expression of TNF, VEGFA, and IL6 in the transplanted tumor cells could be regulated by using Celastrol, and the expression trends were consistent with the in vitro model." (PMID 36506508, 2022). "These neurohormones activate inflammatory mediators such as IL-1, TNF-α, and IL-6, which additionally activate nuclear factor kappa B (NF-ĸB) and signal transducer and activator of transcription 3 (STAT-3)—transcription factors involved in tumor progression." (PMID 36078233, 2022). "PD−L1 expression and PD−1 checkpoint pathway in cancer, autophagy was significantly enriched exclusively in HPV-positive and TNF signaling pathway, cellular senescence, focal adhesion, EGFR tyrosine kinase inhibitor resistance exclusively in HPV-negative tumours." (PMID 35954409, 2022). "For example, activated tumor-infiltrating B cells might secrete cytokines such as IFN-γ and TNF-α to fine-tune the immune context in tumors." (PMID 35133976, 2022). "However, a combination of both antibodies significantly inhibited tumor growth, increased the number of tumor-infiltrating CD8+ T cells, and enhanced IFN-γ and TNF-α production by these T cells." (PMID 35742933, 2022).
tumor (continued). "In the tumor immune microenvironment, NAMPT interacts with inflammatory factors, and many previous studies have shown that extracellular NAMPT promotes the production of many inflammatory factors, such as IL-1α, IL-1β, IL-6, and TNF-α." (PMID 35906622, 2022). "For example, IFN-γ and TNF are also released during a natural immune response involving T helper 1 (TH1) cells (for instance, against tumor cells), although in lower concentrations, or against macrophages infected with Mycobacterium tuberculosis without disinhibition by ICB." (PMID 35563820, 2022). "Upon tumor cell encounter, CAR-T cells release different pro-inflammatory cytokines, such as TNF-α, IFN-ɣ, IL-1, and granulocyte-macrophage colony-stimulating factor (GM-CSF), that leads to macrophage recruitment and activation, causing a dangerous cytokine storm involving IL-6 and GM-CSF." (PMID 35694446, 2022). "Previous studies showed that PD-1 blockade led to the augmentation of effector T cells in tumor sites, increasing the cytolytic activity of tumor-specific cells, increasing production of IL-2, INF-γ, TNF-α, IL-17, and IL-6, and decreasing the production of the Th2 cytokines such as IL-5 and IL-13." (PMID 35996120, 2022). "Second, analyses performed on tumor lysates revealed that chemokines involved in myeloid cell migration (CCL5, CCL2, CCL4), together with inflammatory (IL-1β and TNFα) and pro-angiogenic factors (VEGF-A, VEGFR2, PDGF, Endoglin) were increased in tumors of mice fed a HFHCD." (PMID 36104342, 2022). "Combination of RT with ATRA has shown to induce a marked increase in TNF‐α and inducible nitric oxide synthase as well as inflammatory macrophages in local and distal nonirradiated tumours in a preclinical study of colon adenocarcinoma model." (PMID 35261190, 2022). "At 2 h post injection, a noticeable fluorescence signal was observed in the tumor receiving LNT-SeNPs + TNF-α but not that receiving LNT-SeNPs only." (PMID 36678748, 2022). "In addition, pro-inflammatory cytokines (e.g., IL-6, TNF-α, and IL-1β) induced by ICD, can also help convert an immunosuppressive tumor microenvironment into an immunogenic one." (PMID 36278159, 2022). "Moreover, we also found that the cotreatment of BV6 with TRAIL and TNFα enhances the anti-tumor properties compared to the lone treatment of TRAIL and TNFα." (PMID 36358282, 2022). "Furthermore, they assist tumor initiation and the mutagenic microenvironment by releasing circulating pro-inflammatory cytokines (IL6, TNF-α, and IFN-γ), growth factors (VEGF and EGF), ROS, and proteases." (PMID 35707536, 2022). "Although the exact mechanism has not been elucidated, TNF-signaling in cancer cells has an overall pro-tumor effect, promoting survival, proliferation, and evasion of immune surveillance." (PMID 36591235, 2022). "Likewise, the cells of the tumor located in the primary site produce many factors, such as IL-1, IL-6, IL-11, PDGF, MIP-1α, TNF, M-CFS, RANKL, and PTHrP, directly stimulating osteoclasts to form osteoclastic-type lesions." (PMID 36230523, 2022). "Treatment of an immunocompetent colorectal tumor mouse model with these Man-LF NPs led to a decrease of the tumor volume concomitantly with a downregulation of the M2- related markers and TGFβ expression of TAM while the expression of STAT1 and TNF was increased." (PMID 35163420, 2022). "Furthermore, adenosine signaling through A2BR favors tumor growth by supporting the recruitment of CD11b+Gr1+ MDSCs that impairs tumor infiltration by CD8+ T and NKT cells and their production of TNF-α, IFN-γ, and granzyme B." (PMID 36713558, 2022). "Inflammatory cytokines, such as IL-6, tumor necrosis factor and vascular endothelial growth factor VEGF produced by neutrophils activation may enhance tumor growth." (PMID 35797279, 2022). "The biggest impediment to utilizing the anti-tumor properties of TNF-α is its systemic, non-target effects." (PMID 35740607, 2022).
tumor (continued). "In another mouse study using tumor-bearing IFN-β −/− mice, TANs displayed protumor behavior, such as reduced expression of ICAM-1 and TNF-α and low cytotoxicity toward tumor cells, implying that IFN-β enhances the polarization of TANs toward the antitumor phenotype." (PMID 35328639, 2022). "The OV-infected cancer cells efficiently reactivated TILs, and TNF-α and IFN-γ, which are known to upregulate MHC and costimulatory molecules on the surface of tumor cells and may synergize with OV-OX40L/IL12 to prime a naive T cell." (PMID 35715953, 2022). "TNF-α and IFN-γ are cytokines that play an active role in the anti-tumor immune responses." (PMID 36303207, 2022). "MMP9, which degrades major extracellular structures and releases various signal peptides, is involved in tumor growth and metastasis by regulating epithelial-mesenchymal transition (EMT), stimulating tumor cell survival and invasion in response to TNF-α-induced inflammatory signals." (PMID 36555705, 2022). "While we reported that TNF-α was involved in in vitro killing of tumor cells using anti-TNF-α Abs it is simply not known what the role other mediators elicited from MCs have in apoptosis induction." (PMID 35574362, 2022). "Additionally, the NF-kB-inducing cytokines TNF, TL1A and IL-1β all promote Th9 cell differentiation and specifically enhance the anti-tumor efficacy of Th9 adoptive cellular therapy (ACT)." (PMID 36389679, 2022). "Remarkably, NKp44/PDGF-DD interaction promotes the secretion of IFN-γ and TNF-α by IL-2-activated NK cells, but not cytotoxicity, limiting tumor cell growth in vitro and tumor spread in a transgenic NCR2 mouse model." (PMID 35757695, 2022). "Type 1 T helper cells, which release TNF-a, IL-2, and interferon-g (IFN-g), exert antitumor effects, while Type 2 T helper cells mainly produce IL-4 to suppress the host immune system and promote tumor growth." (PMID 36171881, 2022). "Besides, the functional CD8+ T cells, which produce various cytokines (TNFα, IFNγ, GZMB, and IL2), were increased in the tumor from VEGF-C mRNA group." (PMID 35301438, 2022). "Additionally, CD4+ T cells indirectly mediate the activation and maturation of DCs, which activate CD8+ T cells either by cross-presenting tumor antigens or by producing effector cytokines such as IFN-γ and TNF-α." (PMID 35759090, 2022). "Furthermore, there was downregulated expression of TNF-α, IFN-γ, perforin, and granzyme B in the peripheral blood of tumor-bearing C3H mice in the sh-LINC01123 + miR-214-3p-inhibitor group (P < 0.05)." (PMID 35115487, 2022). "Alongside the secretion of interferon cytokines, detectable traces of the TNF-α are also found from IL-15 activated ILC1 cells, supporting the hypothesis that ILC1 cells suppress early-stage tumours via apoptotic lysis of tumour cells." (PMID 35557940, 2022). "Third, a noncommonly used molecule for mature DC generation was TNF-α, which is involved in the upregulation of the NF-κB pathway and participates in tumor progression and chemo- and immunotherapy resistance in lung adenocarcinoma." (PMID 35589776, 2022). "Following treatment with 1,4-dihydroxy quininib, significant increases in secretion of IL-13, IL-2 and TNF-α are observed in the primary tumour explants, but not in the UM cell lines." (PMID 36698840, 2022). "The regulation of interleukin 17, tumor necrosis factor, hypoxia-inducible factor-1, and MAPK signaling pathways affected central nervous system (CNS) inflammatory response, cellular immunity, tumor-related signaling pathways, protected neurons, and inhibited PND." (PMID 35992596, 2022).
tumor (continued). "Relative to Control, Tumor mice had higher spleen mass, higher burden of total splenic bacteria as detected via FISH staining for global bacterial 16S DNA, and higher splenic production of the pro-inflammatory cytokines IL-6, CXCL1, and MCP-1, but lower TNFα." (PMID 35248004, 2022). "Tumor-related pathways, such as PI3K-Akt, TNF, and NF-κB signaling pathways, may be involved in quercetin treating PTC through KEGG enrichment analysis." (PMID 36510497, 2022). "TNF-α has not a single effect on tumor cells, but can promote tumor cell proliferation and differentiation, as well as inhibit proliferation and induce apoptosis." (PMID 35574296, 2022). "Neutrophils can also elicit tumor-killing functions by the expression of NO, TRAIL, and TNF." (PMID 36031601, 2022). "In addition, tumor biology, TTP as well as vascularization, proliferation, EMT, and extracellular matrix progression are influenced by external factors including VEGF, TNF, and TGF." (PMID 36552039, 2022). "These CAR-T cells could effectively recognize specific cetuximab-bound tumor cells and promote the expression and secretion of INF γ and TNFα by combining cetuximab and CAR-T cells." (PMID 35935930, 2022). "TNFα is a cytokine that can directly kill tumor cells and has no obvious cytotoxicity to normal cells." (PMID 35372072, 2022). "In addition, WT ARI-0001 and TCRKO ARI-0001 CAR-T cells shared a comparable expression of LAG3 and TIM3 exhaustion markers after tumor cells killing as well as similar production of interferon (IFN)-γ and tumor necrosis factor (TNF)-α." (PMID 36275777, 2022). "Tumor microenvironment (TME), another important component in cancer tissue, has been demonstrated to have a strong correlation with EMT through the linkages of proinflammatory factors such as TGF-β, TNF-α, and IL-6." (PMID 36467998, 2022). "We review some beneficial bacteria that act on DCs, NK cells, cytotoxic T cells, and helper T cells to promote the secretion of the pro-tumor cytokines IFN-1, IFN-γ, and IL-2 and down-regulate the secretion of TNF-α, IL-6, IL-10, and IL-22, thus exerting anti-tumor immune effects." (PMID 36438840, 2022). "Additionally, CD8+ Tem also contributed to the TNF signaling pathway, which revealed the positive feedback of CD8+ Tem on tumor invasion." (PMID 36291687, 2022). "In this sense, the M1 phenotype releases IL-12, IFN-γ, TNF-α, IL-1β, ROS, and nitric acid, hence promoting the recruitment and activity of NK cells and CD8 + T cells in the tumor microenvironment to induce an anti-tumor immune function and inflammation." (PMID 35565420, 2022). "As an example, tumor-derived prostaglandin E2 (PGE2) and transforming growth factor- β (TGF- β) synergistically suppress the production of IFN-I and tumor necrosis factor (TNF) in activated pDCs, which then exhibit a tolerogenic phenotype." (PMID 36232698, 2022). "We detected increased levels of cytokines such as IFNγ and TNFα, which could favor the increase in infiltrating CD8+ T cells observed in the tumor regions." (PMID 35326737, 2022). "Interestingly, the role of YTHDF2 was also found to be related to inhibition of tumor necrosis factor (TNF), which subsequently suppressed apoptosis of tumor cells." (PMID 35382893, 2022). "We then analyzed the associations between CXCL2 expression and classical macrophage phenotype markers of M0 (undifferentiated) (AIF1), M1 (anti-tumor) (IL12A, TNF, NOS2, PTGS2) and M2 (tumor-promoting) (IL10, CD163, TGFB1, CSF1R) in TCGA-LIHC cohort with Spearman’s rank correlation test." (PMID 36276119, 2022). "NK cells promote anti-tumor immunity through releasing IFN-γ, TNF-α, granzymes and perforins, but they could transdifferentiate into helper ILC1s (hILC1s ) under activated TGF-β signaling, resulting in impairing NK cell-mediated tumor control." (PMID 36246629, 2022). "This study also demonstrated that LGG induces greater TNF-α production in neutrophils than BCG, which may have a positive effect on tumor regression." (PMID 36140470, 2022).